VIPR2 (vasoactive intestinal peptide receptor 2)
Description:
G protein-coupled receptor activated by the neuropeptides vasoactive intestinal peptide (VIP) and pituitary adenylate cyclase-activating polypeptide (ADCYAP1/PACAP). Binds VIP and both PACAP27 and PACAP38 bioactive peptides with the following order of potency PACAP38 = VIP > PACAP27. Ligand binding causes a conformation change that triggers signaling via guanine nucleotide-binding proteins (G proteins) and modulates the activity of downstream effectors. Activates cAMP-dependent pathway. May be coupled to phospholipase C.
Synonyms: VIP-R-2; PACAP-R-3; PACAP-R3; VPAC2R; VPAC2; C16DUPq36.3; DUP7q36.3; VPCAP2R
Tractability: Small molecule: a high-quality ligand is known. Antibody: its Gene Ontology location is reachable by antibodies, with high confidence; UniProt places it where antibodies can reach, with medium confidence; UniProt predicts a signal peptide or a membrane-spanning region. PROTAC: a small molecule that binds it is known.
Target class: Peptide receptor (family B GPCR); Vasoactive intestinal peptide receptor; Membrane receptor; Family B G protein-coupled receptor
Gene: Protein-coding gene on chromosome 7 (159,028,175 to 159,144,944, reverse strand). Ensembl gene ENSG00000106018.
Subcellular location: Cell membrane
Subcellular location (Human Protein Atlas): Focal adhesion sites
Pathways (Reactome):
Signal Transduction: G alpha (s) signalling events; Glucagon-type ligand receptors
Gene Ontology:
Molecular function: pituitary adenylate cyclase-activating polypeptide receptor activity; protein binding; vasoactive intestinal polypeptide receptor activity; G protein-coupled peptide receptor activity; G protein-coupled receptor activity; peptide hormone binding; transmembrane signaling receptor activity
Biological process: adenylate cyclase-activating G protein-coupled receptor signaling pathway; adenylate cyclase-modulating G protein-coupled receptor signaling pathway; cell-cell signaling; signal transduction; cell surface receptor signaling pathway; G protein-coupled receptor signaling pathway
Cellular component: plasma membrane; membrane
Genetic constraint (gnomAD): Loss-of-function variants: 44 observed, 54.12 expected, observed/expected ratio (o/e) 0.81, 90% interval 0.64 to 1.04. The upper end of that interval is the gene's LOEUF score, 1.04, which puts it in group 4 of 6, group 1 being the genes least tolerant of losing a copy. Missense variants: 501 observed, 528.96 expected, observed/expected ratio (o/e) 0.95, 90% interval 0.88 to 1.02. Synonymous variants: 235 observed, 221.96 expected, observed/expected ratio (o/e) 1.06, 90% interval 0.95 to 1.18.
Homologues: Orthologues: chimpanzee VIPR2 (99% identical), macaque VIPR2 (97% identical), pig VIPR2 (88% identical), rabbit VIPR2 (88% identical), mouse Vipr2 (86% identical), rat Vipr2 (86% identical), guinea pig VIPR2 (84% identical), tropical clawed frog vipr2 (61% identical), zebrafish vipr2 (57% identical). Paralogues in human: ADCYAP1R1 (50% identical), VIPR1 (47% identical), SCTR (45% identical), GHRHR (38% identical), PTH1R (37% identical), GLP1R (35% identical), GLP2R (35% identical), GCGR (34% identical), GIPR (34% identical), PTH2R (32% identical), CALCRL (26% identical), CALCR (25% identical), and 30 more.
Diseases named in the same sentence as VIPR2 in open-access papers:
VIPR2 is named in the same sentence as 87 diseases in open-access papers, as found by Europe PMC text mining. Sharing a sentence is not in itself a finding about the gene and the disease. The quoted sentences say what the papers report.
schizophrenia (21 papers, 2011 to 2023). A major psychotic disorder characterized by abnormalities in the perception or expression of reality. "Mice deficient in Vipr2, which participate in internal rhythm synchronization, exhibit cognitive deficits resembling schizophrenia." (PMID 37506182, 2023). "Several researches have demonstrated a significant association between schizophrenia and microduplications that overlap the vasoactive intestinal peptide receptor 2 gene (VIPR2)." (PMID 37181653, 2023). "Several clinical and preclinical studies have shown that high expression/overactivation of VIPR2 is linked to both schizophrenia and ASD." (PMID 34819858, 2021). "Duplications of the 7q36 region, either including or just upstream of VIPR2, result in upregulation of VIPR2 and cause schizophrenia in patients." (PMID 32973355, 2021). "In particular, microduplications at 7q36.3, which contains VIPR2, have been strongly associated with schizophrenia with odds-ratios of 14.1 and 6.3." (PMID 34819858, 2021). "In this review, we present an overview of human genetic studies implicating VIPR2 CNVs as a risk factor for developing schizophrenia, along basic research findings in mice and cell culture models that provide potential mechanisms to explain the linkage." (PMID 34366784, 2021). "Accumulating evidence in human genetics indicates that microduplications at 7q36.3, containing VIPR2 gene, are linked to schizophrenia and possibly autism spectrum disorder." (PMID 34366784, 2021). "Clinical studies have shown that microduplications at 7q36.3, containing VIPR2, confer significant risk for schizophrenia and autism spectrum disorder (ASD)." (PMID 32581681, 2020). "Among the most highly penetrant genetic risk factors for neuropsychiatric disorders, clinical studies have shown that microduplications at 7q36.3, containing VIPR2, confer significant risk for schizophrenia and ASD." (PMID 32581681, 2020). "The impetus for our studies were the series of reports showing that micro-multiplications of the VIPR2 gene is associated with schizophrenia and ASD, and that these mutations were associated in patients with heightened VIP-induced cAMP responsiveness." (PMID 32581681, 2020). "One of the genes in this interval is VIPR2, duplications of which have recently been implicated in schizophrenia." (PMID 24098143, 2013). "Our findings add new evidence that the functional and probable causative variants of VIPR2 gene may play an important role in susceptibility to schizophrenia." (PMID 37181653, 2023). "Specifically, the non-synonymous mutation rs78564798 (Pallele = 0.006) as well as two rare variations in the VIPR2 gene’s introns (rs372544903, Pallele = 0.026 and a novel mutation, chr7:159034078, GRCh38, Pallele = 0.048) were significantly associated with schizophrenia." (PMID 37181653, 2023). "Interestingly, duplications of the Vipr2 gene were found to confer a significant risk for schizophrenia, thus suggestive of a differential emotional response in the Adnp+/− female mice." (PMID 31534115, 2019). "In addition, it has been shown that copy number variation leading to duplications of the VIPR2 gene contributes to a significant risk for schizophrenia." (PMID 25504760, 2015). "More recently, pathological implications of VIPR2 have been shown in psychiatric disorders in humans, such as schizophrenia, autism spectrum disorder (ASD), depression, and attention deficit/hyperactivity disorder." (PMID 34819858, 2021). "Subsequently, the association between the VIPR2 CNV and schizophrenia were reported in a large scale study of the Han Chinese population." (PMID 34366784, 2021). "At least, our study demonstrates that VIPR2 inhibition is effective against schizophrenia model mice established by VIPR2 overactivation." (PMID 34819858, 2021). "In vivo efficacy of this VIPR2 antagonist also remains to be determined in animal models of psychiatric disorders such as schizophrenia." (PMID 34819858, 2021).
schizophrenia (continued). "Because KS-133 is a selective antagonist of VIPR2 in vitro and in vivo, it would be a good lead molecule for schizophrenia therapy and a tool compound to promote scientific research of VIPR2." (PMID 34819858, 2021). "Further studies on validations of VIPR2’s function in the etiology of schizophrenia are warranted." (PMID 37181653, 2023). "KS-133 may contribute to studies and development of novel schizophrenia therapeutic drugs that target VIPR2." (PMID 34819858, 2021). "Importantly, KS-133 is active in vivo, inhibiting VIPR2-mediated CREB activation and preventing cognitive impairment in a pharmacological model of early postnatal VIPR2 overactivation, a relevant mouse model of schizophrenia." (PMID 34819858, 2021). "In conclusion, we successfully generated KS-133 that may contribute to both the development of a novel drug candidate for the treatment of psychiatric disorders such as schizophrenia and acceleration of basic studies on VIPR2." (PMID 34819858, 2021). "In addition, tandem duplications of the non-coding upstream region of VIPR2 have been observed in cases of schizophrenia and resulted in upregulated VIPR2 expression." (PMID 31417368, 2019). "Vasoactive intestinal peptide receptor 2 (VIPR2) might be an attractive drug target for the treatment of schizophrenia because both preclinical and clinical studies have demonstrated a strong link between high expression/overactivation of VIPR2 and schizophrenia." (PMID 34819858, 2021). "With the identification of rare copy number risk variants implicating specific genes (e.g. VIPR2 and NRXN1) it is increasingly possible to investigate molecular aetiology in patient subgroups to establish whether schizophrenia represents one or many different disease processes." (PMID 22547958, 2011). "In the present review, we aimed to summarize physiological functions of the VPAC2 receptor, recent genetic research linking VIPR2 duplications to schizophrenia, and relevant actions of VPAC2 receptors in animal and cell culture models." (PMID 34366784, 2021).
myopia (6 papers, 2013 to 2024). "Subsequent genotype imputation and single-marker analysis identified two independent groups of VIPR2 variants associated with the qualitative phenotype high myopia: one group of high-risk SNPs and another group of protective variants." (PMID 31796800, 2019). "With this background, we used a candidate-gene approach and identified the VIPR2 gene to be highly associated with high myopia in the Han Chinese population." (PMID 31796800, 2019). "The vasoactive intestinal peptide receptor 2 (VIPR2) gene was identified as a myopia susceptibility locus by our group and another group." (PMID 31796800, 2019). "All these suggested that VIPR2 was a good positional and functional candidate gene for myopia susceptibility." (PMID 31796800, 2019). "Since this is also the first study that has identified VIPR2 as a myopia susceptibility gene, our positive results should be replicated using samples from other populations, particularly those of different ethnicities." (PMID 23637909, 2013). "Of all the 123 possible sliding windows, 2 windows of the FOS gene and 13 windows of the VIPR2 gene displayed significant association (Paemp<0.05) with high myopia even after correction for multiple comparisons (n = 123) by permutation test." (PMID 23637909, 2013). "Additionally, SNP rs6979985 of the VIPR2 gene was found to be associated with high myopia in a Chinese Han cohort." (PMID 36979429, 2023). "One example is rs2730260, an SNP in an intron of VIPR2 that has been implicated in myopia." (PMID 36277849, 2022). "Independently and simultaneously, another group used a hypothesis-free approach and conducted meta-analysis of GWAS, and also found a single SNP (rs2730260; overall P = 8.98 × 10−14) within the VIPR2 gene highly associated with high myopia in Han Chinese26." (PMID 31796800, 2019). "However, we were able to replicate significant haplotype association (Paemp<0.05) of VIPR2 with high myopia: five significant haplotype windows for the replication sample set and six significant haplotype windows for the combined sample set." (PMID 23637909, 2013). "Therefore, we selected EGR1, FOS, JUN, VIP and VIPR2 as functional candidates and investigated their potential association with high myopia." (PMID 23637909, 2013). "In light of the significant association between VIPR2 gene polymorphisms with high myopia, this hypothesis is worth exploring in future studies." (PMID 23637909, 2013). "Therefore, we speculate that VIPR2 may influence genetic susceptibility to myopia through its involvement in circadian rhythms." (PMID 23637909, 2013). "However, we identified VIPR2 as a novel myopia susceptibility gene." (PMID 23637909, 2013). "Animal studies demonstrated a refractory shift towards myopia for the cohort of Vipr2 knockout mice." (PMID 36979429, 2023). "As a logical step forward in elucidating the genetic network involving VIPR2 in the medium term and the etiology of myopia in the long run, we set out to fine-map this region with a view to identifying putative causal variants." (PMID 31796800, 2019). "The expression of VIPR2 in the retina and the choroid was altered in chicks with form-deprivation myopia." (PMID 23637909, 2013). "An unselective antagonist of VIP receptors (including VIPR2) could also suppress the development of form-deprivation myopia in chicks in a dose-dependent manner." (PMID 23637909, 2013). "The expression of VIPR2 in the retina and the choroid was up-regulated in the treated eyes with reference to the fellow control eyes, but down-regulated with increasing axial length in chicks with form-deprivation myopia." (PMID 23637909, 2013). "Researchers indicate that PAX6 rs644242, ZC3H11B rs4373767 and BICC1 rs7084402, VIPR2 rs885863 and rs6979985, ZMAT4 rs7829127, TNKS rs4840437 and rs6989782, PDGFRA rs2114039, SOX2 rs4575941, FGF10 rs339501, rs2973644, and rs 79002828 are associated with severe myopia (moderate and extreme myopia)." (PMID 38660258, 2024).
myopia (continued). "Loss of VIPR2 function may impair bipolar cell function, which corresponds to an increase in form deprivation myopia (FDM), and thus the VIP-VIPR2 signaling pathway axis is a viable new target to control the development of this condition." (PMID 37740201, 2023).
colitis (5 papers, 2019 to 2025). Inflammation of the colon. "On the other hand, models of DSS-induced colitis in Vipr1-/- and Vipr2-/- mice displayed opposite results." (PMID 34322118, 2021). "In fact, Vipr1-/- mice showed a milder disease score compared to wild type mice, whereas Vipr2-/- developed a more severe colitis." (PMID 34322118, 2021).
lung carcinoma (4 papers, 2015 to 2022). "Early in 2017, researchers from Sungkyunkwan University confirmed that VIPR2 is associated with lung cancer at the DNA methylation level." (PMID 35155435, 2022). "For genes that have been identified to be potential lung cancer drivers at transcriptomics and post-transcriptomics levels, only one gene, namely, VIPR2 (ENSP00000262178), was identified as multi-omics level regulator." (PMID 35155435, 2022). "Several genes, such as HOXC12, HAND1, VIPR2, KRT20, MMP24, and VIPR2, were discovered, and their special roles at different omics levels of lung cancer were confirmed." (PMID 35155435, 2022).
asthma (3 papers, 2013 to 2024). "The results confirmed that after stimulating the large intestine by Mangxiao or Dahuang, SP, NK1R, VIP, VIPR1, and VIPR2 were all significantly increased in large intestine tissue of rats with COPD and mice with asthma." (PMID 24023578, 2013).
attention deficit-hyperactivity disorder (3 papers, 2017 to 2023). A disorder characterized by a marked pattern of inattention and/or hyperactivity-impulsivity that is inconsistent with developmental level and clearly interferes with functioning in at least two settings (e.g. at home and at school). "In a study using the 450k array, lower VIPR2 methylation was found in the saliva of children with attention deficit hyperactivity disorder (ADHD), relative to controls, albeit at different sites than those identified in the present study." (PMID 29016858, 2017). "In another genetic analysis, VIPR2 SNPs were found to be significantly associated with depression (including bipolar disorder) and hypomethylation at CpG sites of VIPR2 was observed in DNA samples derived from the saliva of children with attention-deficit/hyperactivity disorder." (PMID 34366784, 2021).
breast carcinoma (3 papers, 2022 to 2025). "Studies have shown that VIPR2 overexpression promotes cell proliferation in breast cancer cell lines and exacerbates tumor growth in vivo." (PMID 39869563, 2025). "In breast cancer, VIP receptor 2 (VIPR2) has been shown to promote cell proliferation and tumor growth through the cAMP/PKA/ERK signaling pathway." (PMID 39869563, 2025). "All cancer cell lines examined in this study expressed VIPR2 mRNA, and VIPR2 protein was detected in MCF-7 and MDA-MB-231 cells (human breast cancer cell lines) and HeLa cells (human cervical cancer cell line)." (PMID 36237322, 2022). "We found that silencing of VIPR2 in MDA-MB-231 and MCF-7 human breast cancer cells inhibited VIP-induced cell migration." (PMID 36237322, 2022).
prostate carcinoma (3 papers, 2012 to 2019). A carcinoma that arises from epithelial cells of the prostate gland. "In the same way as ADRB2, VIP receptors VIPR1 and VIPR2 are expressed in prostate cancer and engage PKA/pS75BAD mechanism to inhibit apoptosis in prostate cancer cells." (PMID 30871232, 2019).
cocaine dependence (2 papers, 2023 to 2024). A psychologically and socially impaired state, with or without physiological changes, that develops as a result of using cocaine and which leads to compulsive behaviors to acquire the substance. "VIPR2, which was strongly associated with narcotic drug addiction in females, has been associated with opioid addiction and cocaine dependence in previous studies." (PMID 39766481, 2024).
neuroblastoma (2 papers, 2013 to 2024). Neuroblastoma (NB) is the most common solid, extracranial childhood tumor. "Upregulated mRNAs, including SKA3, PLOD2, VIPR2, and GGT5, are implicated in neuroblastoma." (PMID 38892402, 2024).
adenoma (1 paper, 2025). A neoplasm arising from the epithelium. "The SEPT9 and VIPR2 promoters were not methylated in low-grade adenomas but were methylated in high-grade adenomas and adenocarcinomas." (PMID 41291100, 2025).
Alzheimer disease (1 paper, 2025). A progressive, neurodegenerative disease characterized by loss of function and death of nerve cells in several areas of the brain leading to loss of cognitive function such as memory and language. "A deletion and an insertion were detected within a dark region of an intronic SVA retrotransposon within vasoactive intestinal peptide receptor 2 (VIPR2), near an Alzheimer's disease‐associated SNP overlapping a deletion present in 10 out of 18 brains analyzed." (PMID 41235755, 2025).
autism (1 paper, 2019). Persistent deficits in social interaction and communication and interaction as well as a markedly restricted repertoire of activity and interest as well as repetitive patterns of behavior. "VIPR2 is located in the subtelomeric region of chromosome 7 and VIPR2 duplications were indicated in the etiology of autism." (PMID 31689297, 2019).
chronic bronchitis (1 paper, 2018). A type of chronic obstructive pulmonary disease characterized by chronic inflammation in the bronchial tree that results in edema, mucus production, obstruction, and reduced airflow to and from the lung alveoli. "However, receptors for VIP (vasoactive intestinal peptide receptor 1 (VPAC), vasoactive intestinal peptide receptor 2 (VPAC2)) were elevated in the epithelium and glands in biopsies from smokers with chronic bronchitis." (PMID 30081920, 2018).
Epileptic encephalopathy (1 paper, 2018). A condition in which epileptiform abnormalities are believed to contribute to the progressive disturbance in cerebral function. "The top-ranked probes related to 25 genes including HNRNPL, RASSF5, CD3D and KALRN involved in immune signalling pathways, in addition to TBC1D24, FBXO9 and VIPR2 previously linked to epileptic encephalopathy." (PMID 29484035, 2018).